HIF1A (hypoxia inducible factor 1 subunit alpha)
Diseases named in the same sentence as HIF1A in open-access papers (continued):
Sharing a sentence is not in itself a finding about the gene and the disease.
colon carcinoma (continued). "Elevated levels of HIF-1α and HIF-2α were shown to simulated the transcription of the PROM1 gene at the P5 promoter in colon cancer cells; specifically, it was initiated by the binding of the HIF-1-Elk1 complex to the E-twenty-six (ETS)-binding motif present in P5." (PMID 38532366, 2024). "In xenograft models of tumors formed by colon cancer cells depleted of NRF2 function, tumors were smaller and developed fewer blood vessels, compared to control tumors, depending on the reduced expression of HIF-1α." (PMID 39062921, 2024). "In vitro studies with colon cancer cells showed that HIPK2 binds, along with HDAC1, to the HIF-1α gene promoter repressing the HIF-1-mediated transcription of VEGF, in line with data showing that the HIPK2/HDAC1 complex leads to histone deacetylation and control of gene transcription." (PMID 39062921, 2024). "The inhibition of the Nrf2 pathway could block the accumulation of HIF-1α in colon cancer cells, inhibit the expression of VEGF and HIF-1α target genes, and reduce the growth of xenograft tumors and angiogenesis under hypoxic conditions in mice." (PMID 39199256, 2024). "Vice versa, we found that a lack of USP10 in different colon cancer cells promoted translation of HIF-1α via mTOR/S6K signaling and at the same time tumorigenesis." (PMID 37371055, 2023). "The usage of LW6 in the colon cancer cells has been shown to promote the degradation of HIF‐1α by upregulation of VHL without affecting HIF‐1β expression, giving rise to competent anti‐tumor efficacy in vivo." (PMID 37334735, 2023). "Similarly, the parathyroid hormone-related protein (PTHrP) is involved in the expression of MMP-9, VEGF, and HIF-1α through the PI3K/AKT and ERK1/2 signaling pathways in colon cancer Caco-2 and HCT-116 cells." (PMID 38069210, 2023). "Investigating the effects of PDT using Me-ALA (a pro-drug of PS PpIX) on human colon cancer spheroids, it was discovered that the PDT resistance phenotype was due to the highly regulated transcriptional activity of hypoxia-inducible factor-1α (HIF-1α)." (PMID 38201494, 2023). "Finally, our research demonstrated that miR-148a downregulated HIF-1α/VEGF and Mcl-1 by directly targeting ROCK1/c-Met to decrease angiogenesis and increase the apoptosis of colon cancer cells." (PMID 35997665, 2022). "In addition, activated KRAS has been shown to induce HIF1A and ARNT target gene expression in human colon cancer cells." (PMID 34580712, 2022). "The expression of Twist is regulated by HIF-1α, which can regulate the expression of Twist by directly binding to the hypoxia-responsive element (HRE) in the proximal promoter of Twist in the hypoxic environment of colon cancer cells." (PMID 36187789, 2022). "In addition, in colon cancer cells, AKT2-HK2-NF-κB/HIF1α/MMP2/MMP9 axis increased the invasion, tumorigenesis, and metastasis of in vitro and promotes lung metastasis in nude mice in vivo." (PMID 35953860, 2022). "In addition to chemoresistance, TRPC5 expression was observed to be positively correlated with high proliferative, migratory, and invasive abilities of colon cancer cells, promoting the EMT through the HIF-1α-Twist signalling pathway." (PMID 35806388, 2022). "Matrine could drastically decreased HIF-1α and its downstream regulatory targets of glucose metabolism such as GLUT1, HK2 and LDHA in HCT116 and SW620 colon cancer cells, thus reversing the Warburg Effect." (PMID 36339566, 2022). "Moreover, in breast and colon cancer cells, PARP-7 acts to suppress multiple oncogenic transcription factors, including HIF-1α, to reduce tumorigenesis." (PMID 33475085, 2021). "Although the relationship between KLF5 and HIF-1α in gastric cancer is not well defined, KLF5 is a known transactivator of HIF-1α in colon cancer." (PMID 33321708, 2020).
colon carcinoma (continued). "Another pathway through which ZFP91 may promote angiogenesis is hypoxia-induced factor 1α (HIF1α), which is strongly upregulated by ZFP91 in colon cancer cells." (PMID 32630670, 2020). "Consistent with previous research, our study showed that HIF-1α expression was attenuated in MCU-silenced HCT-116 and SW-480 cells, indicating that HIF-1α could be a target of MCU in colon cancer." (PMID 32152662, 2020). "Similarly, GEPIA database also revealed that HIF1A expression positively correlated with HK2 and LDHA in colon cancer, rectal cancer and CRC, respectively." (PMID 33218358, 2020). "Reportedly, TRAF6 is a K63-E3 ubiquitin ligase that ubiquitinates and stabilizes HIF-1α in colon cancer cells independent of oxygen." (PMID 33142239, 2020). "In human colon cancer cells (HT-29), garcinol treatment was shown to inhibit angiogenesis and proliferation via downregulating expression of mPGES-1, HIF-1α, CXCR4, MMP-2, VEGF, and MMP-9 via suppression of mPGES-1/PGE2/HIF-1α signaling pathway." (PMID 32365899, 2020). "We previously demonstrated that NRF2-silenced colon cancer cells failed to accumulate HIF-1α under hypoxic conditions, and thus tumor angiogenesis was blocked by NRF2-inhibition." (PMID 31078780, 2019). "Another study linked HIF1α as a major mediator of enhanced TRAIL-R4 production, but not other TRAIL-Rs, at the cell surface of colon cancer cells." (PMID 31333662, 2019). "Expression of the cellular prion protein (PrPc) was shown to be enhanced by HIF1α under hypoxia and to mediate TRAIL resistance in colon cancer cells in vitro and in vivo and may involve enhanced Akt and Bcl-2 activity." (PMID 31333662, 2019). "In case of colon cancer 12 patients were those having high expression of HIF-1α and MDR1 while 15 were those with high expression of LAPTM4B also harboring high expression of MDR1 and HIF-1α." (PMID 30746305, 2019). "To investigate whether the effect of matrine on reversing Warburg effect and inhibiting colon cancer growth is due to the inhibition on HIF-1α, we used shRNA to knockdown endogenous HIF-1α expression in HCT116 and SW620 cells." (PMID 31849679, 2019). "In this study, we examined the effects of stable HIF-1α or HIF-2α siRNA knockdown on autophagy and drug resistance displayed by RAS-driven and BRAF-driven human colon carcinoma cell lines and in patient-derived primary colon cancer cells." (PMID 31151160, 2019). "Therefore, we have selected FBXL5 gene, which showed over three folds decrease upon AM404 treatment, functioned as an oncogene in the progression of colon cancer through regulating PTEN/PI3K/AKT signalling and HIF-1α transcriptional activity." (PMID 31906201, 2019). "Since EPO was induced by HIF-1α, we further examined whether vanillic acid suppressed EPO and VEGF transcription in human colon cancer HCT116 cells." (PMID 30678221, 2019). "To determine whether HIF-1α protein was regulated by PTBP3 in colon cancer, we detected the expression of HIF-1α in PTBP3 OE and KD colon cancer cells." (PMID 31291975, 2019). "In this respect, we have also reported that under normoxic conditions colon cancer cells coexpress HIF-1α and HIF-2α, compared to non-malignant colon cells, which do not express these factors under the same conditions." (PMID 31151160, 2019). "Hence, this study was aimed to measure the co-expression of HIF-1α, MDR1 and LAPTM4B genes in blood of breast, ovarian, prostate and colon cancer patients and matched with appropriate controls." (PMID 30746305, 2019). "To determine whether KL regulated HIF1α, we overexpressed constitutive active form of ERK-MAPK kinase ERK2 (ERK2E322K) into colon cancer cells." (PMID 29884183, 2018). "In agreement with this interpretation, PIN1 was shown to contribute to angiogenesis in colon cancer cells by interacting with hypoxia-inducible factor (HIF)-1α in a phosphorylation-dependent manner, leading to HIF-1α stabilization and increased transcriptional activation of VEGF." (PMID 30314361, 2018).
colon carcinoma (continued). "In colon cancer cells, NHERF1 expression could be increased by the activation of NF-κB signaling and/or the multiple downstream signaling pathway of HIF-1α/VEGF-A induced in the hypoxia microenvironment." (PMID 27999191, 2017). "Moreover, in 27.27% of human colon cancer, ZFP91 and HIF-1α were collectively up-regulated (p=0.009)." (PMID 27144516, 2016). "In chronic hypoxia (over 8 h at 1% O2), HIF-2α but not HIF-1α gradually accumulated in colon cancer cells." (PMID 27793037, 2016). "In addition, PD98059, a MEK inhibitor, was previously shown to block HIF-1α protein synthesis and inhibit HIF-stimulated VEGF expression in human colon cancer cells treated with IGF-1." (PMID 26882567, 2016). "Furthermore, IHC assay showed that areas of strong ZFP91 signals displayed intense HIF-1α, VEGF and CD31, whereas areas with knockdown of HIF-1α exhibited lower HIF-1α, VEGF and CD31 staining signals in ZFP91-overexpressing colon cancer cells." (PMID 27144516, 2016). "In addition, we have utilized a HIF-1α luciferase reporter gene construct, 5xHRE-ODD-luc, stably transfected into human colon cancer (HCT116) cells (HCT116/5xHRE-ODD-luc)." (PMID 26784107, 2016). "For example, in contrast to the previous report that ILK increased transcription of the Snail gene in human colon carcinoma cells, the present study indicates that ILK promoted the upregulation of Snail via multiple pathways involving HIF-1α, YB-1, and GSK3β at different cellular levels." (PMID 25821081, 2015). "The increase of HIF-1α expression under hypoxia was reported to be inhibited by LW6 through the overexpression of VHL, leading to the inhibition of tumor angiogenesis in the HCT116 human colon cancer cell line." (PMID 26017562, 2015). "In this respect, we also showed that only colon carcinoma cells co-express HIF-1α and HIF-2α under normoxic conditions, in contrast to non-malignant colon cells, which do not express these factors under these conditions." (PMID 25396735, 2014). "Taken together, these results clearly indicated that both HIF-1α and HIF-2α play key roles in promoting the in vivo aggressiveness and tumor growth of both CD44+ and CD44−/CD133− subpopulations isolated from SW480 colon cancer cells, which exhibit constitutively active Wnt signaling." (PMID 25396735, 2014). "Likewise, it has been previously shown that caffeine inhibits adenosine-induced accumulation of HIF-1α and VEGF-A in colon cancer cells." (PMID 24595168, 2014). "We found that 15-LOX-1 reexpression in HCT116, HT29LMM, and LoVo colon cancer cells inhibited survival, vascular endothelial growth factor (VEGF) expression, angiogenesis, cancer cell migration and invasion, and HIF-1α protein expression and stability under hypoxia." (PMID 24634093, 2014). "They suggested that MMP-2, HIF-1α and VEGF might represent useful parameters for detection of early carcinogenesis and progression of colon carcinoma." (PMID 24153191, 2013). "Next we examined whether HIF-1α and HIF-2α bind to the CD133 P5 −98 bp promoter through ETS proteins in human colon cancer WiDr cells that express abundant CD133 mRNA and protein." (PMID 23840432, 2013). "Subsequently, we investigated the binding of HIF-1α and HIF-2α at EBS and whether HIF-1α and HIF-2α regulate the expression of CD133 in colon cancer cells." (PMID 23840432, 2013). "Furthermore, the findings also revealed high incidence of HIF-2α and co-expression of HIF-1α and HIF-2α in ccRCC compared to head & neck and colon cancers." (PMID 22804960, 2012). "PFKFB4 is strongly induced by hypoxia through an hypoxia inducible factor 1 alpha (HIF1A) subunit dependent mechanism, and might contribute significantly to the Warburg effect observed in malignant gastric, pancreatic, breast and colon tumors." (PMID 20059769, 2010).
colon carcinoma (continued). "Statistical analysis shows that the incidence of lymph node metastasis tends to be higher in patients with colon cancer with high rather than low expression of HIF-1α, CXCR4, or VEGF (P < .001, P = .001, P = .001, resp.)." (PMID 20953377, 2010). "The experiment results demonstrated that CXCR4 mRNA and VEGF mRNA expression levels were significantly higher in fresh colon cancer samples than in normal colonic tissue, whereas tumoral HIF-1α expression at the mRNA levels was not higher." (PMID 20953377, 2010). "The mRNA expression of HIF-1α, CXCR4, and VEGF in colon cancer were quantified by real-time PCR." (PMID 20953377, 2010). "Furthermore, we analyzed the clinicopathologic significance of combined HIF-1α, CXCR4, and VEGF expression in colon cancer." (PMID 20953377, 2010). "Therefore, we analyzed the correlation between the high expression of both HIF-1α and CXCR4 and clinicopathologic significance in human colon cancer samples." (PMID 20953377, 2010). "Statistical analysis showed that combined high expression of all three molecules (HIF-1α, CXCR4, and VEGF) is significantly associated with lymph node metastasis in patients with colon cancer as compared with cases not showing such expression (P < .001)." (PMID 20953377, 2010). "The data show that both HIF-1α and HIF-2α are expressed at similar frequencies in colon cancer." (PMID 19844231, 2009). "Thioredoxin transfection has been shown to increase HIF1α transactivation activity and the protein products of hypoxia-responsive genes such as VEGF and nitric-oxide synthase in MCF7 breast and HT29 colon cancer cell lines under both aerobic and hypoxic conditions." (PMID 15655539, 2005). "However, the subsequent experimental results showed that knockdown or overexpressing ONECUT3 in colon cancer cells did not affect the mRNA or protein expression of HIF-1α." (PMID 40032849, 2025). "In agreement, tumor xenografts established from colon cancer cells depleted of HIPK2 function, compared to control ones, showed that HIPK2 knockdown increases tumor vascularity and blood density, as evaluated by immunohistochemical analysis and by HIF-1α and VEGF up-regulation at the mRNA levels." (PMID 39062921, 2024). "As a matter of fact, HIF-1α is induced by KRASG12V at transcription level and overexpression of HIF-1α under hypoxia could increase KRASG12V activity and triggers its downstream signaling in colon cancer cells through a positive feedback loop." (PMID 33691728, 2021). "Finally, we immunostained colon cancer TMAs for PTBP3 and HIF-1α to assess whether PTBP3 regulated HIF1a in human colon cancers, The results showed that PTBP3 expression strongly correlated with HIF-1α IHC scores in colon cancer tissues." (PMID 31291975, 2019). "Furthermore, we also demonstrated that HIF‐1α was not directly target gene of miR‐148a using the luciferase assay in the both colon cancer cell lines." (PMID 30834693, 2019). "Moreover, the influences of OA on the levels of HIF1α, FASN and CPT1 in the high-fat diet group were more obvious than those in the normal diet group, suggesting that high activity of lipid metabolism made colon cancer cells more sensitive to OA." (PMID 28594405, 2017). "Naturally, the overexpression of HIF-1α upregulated VEGF and EPO protein and mRNA levels in the cells (lane 5), silencing of HIF-1α abolished the upregulation of VEGF and EPO protein and mRNA levels mediated by ZFP91 (lane 4), supporting that ZFP91 is able to upregulate HIF-1α in colon cancer cells." (PMID 27144516, 2016).
colon carcinoma (continued). "Indeed our findings showed that HIF-1α protein expression was suppressed by CBF as early as 6 hours after treatment in both colon cancer cell lines, regardless of the elevation of mRNA transcript." (PMID 23818933, 2013). "Therefore, we provide clinical evidence that coexpression of HIF-1α and VEGF may play an important role in colon cancer growth and lymph node metastasis." (PMID 20953377, 2010). "Furthermore, we investigate whether the expression of HIF-1α, CXCR4, and VEGF have a significant correlation with clinicopathologic factors of colon cancer." (PMID 20953377, 2010). "However, the loss of HIF-2α expression, but not HIF-1α, was strongly linked to advanced tumour stages, suggesting that HIF isoforms may have different cellular functions in colon cancer." (PMID 40917756, 2025). "Our experiments revealed that KynA treatment downregulates HIF-1α expression levels of protein in colon cancer cells without affecting HIF-1α mRNA expression, indicating a post-transcriptional regulation of HIF-1α." (PMID 39920992, 2025). "There were no large differences in cell viability between HIF-1α and HIF-2α in ovary and colon cancer cells." (PMID 32847073, 2020). "We have previously reported that HIF-1α and HIF-2α are co-expressed in colon cancer cells but not in nonmalignant 112CoN cells under normoxic conditions." (PMID 31151160, 2019). "However, in contrast to LPS treatment, exposure of MC-38 colon carcinoma cells to hypoxia for 0.5 to 4 hours did not induce nuclear translocation of p65/RelA as shown by immunofluorescence and immunoblotting of nuclear extracts, although HIF-1α proteins levels were stabilized under these conditions." (PMID 25978030, 2015). "Under normoxia, we determined that both HIF-1α and HIF-2α are expressed in human colon cancer cells but not in their non-malignant counterparts." (PMID 25396735, 2014). "However, in tumor cells such as colon cancer cells, SIRT6 binds directly to the hypoxia-responsive elements of the glycometabolism genes and blocks HIF-1α-induced glycometabolism without activating oncogenic pathway." (PMID 33109235, 2020). "In addition, there were no significant cell viability differences between HIF-1α and HIF-2α in SKOV3, SNU840 (Ovary cancer), and CT26, HCT116 (Colon cancer)." (PMID 32847073, 2020). "Similarly, four additional human colon cancer cell lines (COLO-741, HT-29, SW-620 and CX-1) showed no HIF-1α mRNA upregulation following LPS treatment (data not shown)." (PMID 25978030, 2015).